TOMM70 (translocase of outer mitochondrial membrane 70)
Description:
Acts as a receptor of the preprotein translocase complex of the outer mitochondrial membrane (TOM complex). Recognizes and mediates the translocation of mitochondrial preproteins from the cytosol into the mitochondria in a chaperone dependent manner. Mediates TBK1 and IRF3 activation induced by MAVS in response to Sendai virus infection and promotes host antiviral responses during virus infection. Upon Sendai virus infection, recruits HSP90AA1:IRF3:BAX in mitochondrion and the complex induces apoptosis.
Synonyms: KIAA0719; TOM70; TOMM70A
Tractability: Antibody: UniProt predicts a signal peptide or a membrane-spanning region. PROTAC: UniProt records ubiquitination sites on it; ubiquitination databases record sites on it.
Gene: Protein-coding gene on chromosome 3 (100,363,431 to 100,401,111, reverse strand). Ensembl gene ENSG00000154174.
Subcellular location: Mitochondrion outer membrane
Subcellular location (Human Protein Atlas): Mitochondria
Pathways (Reactome):
Disease: SARS-CoV-1 activates/modulates innate immune responses; SARS-CoV-2 activates/modulates innate and adaptive immune responses
Autophagy: PINK1-PRKN Mediated Mitophagy
Immune System: DDX58/IFIH1-mediated induction of interferon-alpha/beta
Metabolism of proteins: Ub-specific processing proteases
Protein localization: Mitochondrial protein import
Gene Ontology:
Molecular function: protein binding; protein-macromolecule adaptor activity; protein transmembrane transporter activity
Biological process: activation of innate immune response; cellular response to virus; positive regulation of defense response to virus by host; positive regulation of interferon-beta production; regulation of apoptotic process; protein import into mitochondrial matrix; protein insertion into mitochondrial inner membrane; protein insertion into mitochondrial outer membrane; protein localization to mitochondrion; negative regulation of cell growth involved in cardiac muscle cell development; positive regulation of establishment of protein localization to mitochondrion; regulation of multicellular organismal process; response to thyroxine
Cellular component: extracellular exosome; membrane; mitochondrial membrane; mitochondrial outer membrane; mitochondrion; mitochondrial outer membrane translocase complex; TOM complex
Genetic constraint (gnomAD): Loss-of-function variants: 10 observed, 56.91 expected, observed/expected ratio (o/e) 0.18, 90% interval 0.11 to 0.3. The upper end of that interval is the gene's LOEUF score, 0.3, which puts it in group 1 of 6, group 1 being the genes least tolerant of losing a copy. Missense variants: 556 observed, 682.72 expected, observed/expected ratio (o/e) 0.81, 90% interval 0.76 to 0.87. Synonymous variants: 239 observed, 243.59 expected, observed/expected ratio (o/e) 0.98, 90% interval 0.88 to 1.09.
Homologues: Orthologues: chimpanzee TOMM70 (99% identical), macaque TOMM70 (99% identical), pig TOMM70 (98% identical), guinea pig TOMM70 (98% identical), dog TOMM70 (97% identical), rabbit TOMM70 (97% identical), mouse Tomm70a (93% identical), rat Tomm70 (93% identical), tropical clawed frog tomm70 (80% identical), zebrafish tomm70a (79% identical), Drosophila melanogaster Tom70 (38% identical). Paralogues in human: TTC12 (17% identical), DNAAF4 (15% identical), SPAG1 (13% identical), RPAP3 (12% identical), UNC45A (12% identical), UNC45B (12% identical), STIP1 (10% identical), TOMM34 (8% identical), SPATA16 (8% identical), TTC1 (7% identical), ST13 (6% identical), TTC31 (6% identical), and 6 more.
Diseases named in the same sentence as TOMM70 in open-access papers:
TOMM70 is named in the same sentence as 33 diseases in open-access papers, as found by Europe PMC text mining. Sharing a sentence is not in itself a finding about the gene and the disease. The quoted sentences say what the papers report.
viral infection (9 papers, 2020 to 2025). "A previous report showed that TOMM70 acts as receptor of the MT antiviral-signaling protein (MAVS) and thereby participates in the corresponding system of innate immunity against viral infections." (PMID 34368262, 2021).
schizophrenia (2 papers, 2020 to 2021). A major psychotic disorder characterized by abnormalities in the perception or expression of reality. "The gene–disease analysis further revealed that the ATP6V1A/BNIP3 and CAMK4/TIPRL/TOMM70 signatures were associated with several brain-related disorders, including developmental disabilities, schizophrenia, intellectual disabilities, abnormal cerebral white matter morphology, and mental retardation." (PMID 34683848, 2021).
hereditary spastic paraplegia (1 paper, 2025). Hereditary spastic paraplegias (HSP) comprise a genetically and clinically heterogeneous group of neurodegenerative disorders characterized by progressive spasticity and hyperreflexia of the lower limbs. "TOMM70 is a receptor at the contact site between mitochondria and the endoplasmic reticulum, and TOMM70 has been identified as a risk gene for hereditary spastic paraplegia." (PMID 40151845, 2025). "Thus, in zebrafish, a mutation in the endoplasmic reticulum-mitochondria contact site protein Tomm70 recreates some of the neurodegenerative phenotypes characteristic of hereditary spastic paraplegia." (PMID 40151845, 2025).
infection (7 papers, 2020 to 2025). The state of being infected such as from the introduction of a foreign agent such as serum, vaccine, antigenic substance or organism. "ORF9b protein hijacking of the outer mitochondrial membrane protein TOMM70 is reported to be one of the key viral‐mitochondrial interactions occurring during infection; however, much about this interaction remains unclear, and currently, it is captured in only one structure." (PMID 34519429, 2021).
cancer (4 papers, 2020 to 2024). A tumor composed of atypical neoplastic, often pleomorphic cells that invade other tissues. "It remains unknown whether this innate immune function of TOMM70 is correlated with the better prognosis of cancers upregulating TOMM40 complexes." (PMID 34368262, 2021).
TOMM70 also shares sentences with these, for which no sentence is quoted: cardiac hypertrophy (4 papers); breast carcinoma (3); heart failure (3); Parkinson disease (3); COVID-19 (2); Down syndrome (2); lactic acidosis (2); renal carcinoma (2); anemia (1); Ataxia (1); autism spectrum disorder (1); cardiac diseases (1); cognitive deficits (1); dementia (1); developmental delays (1); developmental disabilities (1); diabetes (1); diabetic cardiomyopathy (1); diabetic foot ulcers (1); Dystonia (1); endothelial dysfunction (1); epilepsy (1); intellectual disabilities (1); ischemia (1); lung carcinoma (1); microcephaly (1); myocardial infarction (1); myocardial ischemia (1).